JUNB (JunB proto-oncogene, AP-1 transcription factor subunit)
Diseases named in the same sentence as JUNB in open-access papers (continued):
Sharing a sentence is not in itself a finding about the gene and the disease.
psoriasis (continued). "Skin tissues of JunB/c-Jun double-mutant (DKO) mice show elevated levels of S100A9 proteins, and in humans genes encoding these proteins are localized in the psoriasis susceptibility region PSORS410." (PMID 27698489, 2016). "Several TFs/uDBPs additionally showed altered expression in blood from psoriasis patients (increased: JUNB, STAT3, DTL, CAT; decreased: CUX2, ZNF559, AVEN, RUVBL1, RAN)." (PMID 25883770, 2015). "These mice develop a psoriasis-like skin disease upon tamoxifen (Tx)-induced deletion of Jun and JunB in the epidermis with K5-creER." (PMID 25216727, 2014). "Both JunB and c-Jun are highly expressed in lesional skin, but levels of JunB have been shown to be low in severe psoriasis and intermediate in mild psoriasis, while c-Jun is expressed in the opposite manner." (PMID 21977313, 2011). "The deletion or reduction of JunB in the epithelial cells of mice led to psoriasis, systemic lupus erythematosus like disease, and myeloproliferative disease, which could probably be explained by elevated cytokines G-CSF and lL-6." (PMID 38384322, 2023). "To investigate, whether extrinsic factors influence CD8α cDC1 differentiation we used a mouse model with deletion of c-Jun/JunB restricted to keratinocytes (c-Jun/JunBΔ/ΔK5-CreER) that results in a psoriasis-like skin inflammation." (PMID 33758366, 2021). "The role of JunB in psoriasis-like skin disease and arthritis was also reported." (PMID 33802099, 2021). "In contrast to its therapeutic effect in both keratinocyte-driven psoriasis models, the c-Jun/JunB model and mouse-tail test, dithranol did aggravate psoriatic lesions in the imiquimod model that has been solely shown to be immunologically mediated and dependent on the IL-17/IL-23 axis." (PMID 32484435, 2020). "The differential expression of c‐JUN and JUNB in CD200+/K15+ bulge HF‐SCs in human samples of psoriatic plaques directed us to explore the potential causal contribution of epidermal stem cell populations to the initiation and development of psoriasis." (PMID 31556482, 2019). "Furthermore, anti-VEGF-A antibody treatment strongly reduced skin inflammation, as well as the number and size of blood vessels, in a mouse model in which epidermal-specific deletion of c-Jun and JunB leads to a psoriasis-like skin inflammation." (PMID 24695674, 2014). "In addition, simultaneous conditional deletion of c-jun and JunB in the epidermis produces a psoriasis-like phenotype." (PMID 23762562, 2013). "Furthermore, in mice, double knockout of JunB and c-Jun leads to a skin phenotype with altered KC differentiation, which was suggested to mimic some features of human psoriasis." (PMID 23915137, 2013). "For example, in mice, epidermal deletion of JunB, which in humans is localized to the so-called psoriasis susceptibility region PSORS6, along with deletion of its functional homologue c-Jun, leads to skin inflammation with histological and molecular hallmarks of human psoriasis." (PMID 27698489, 2016). "Also, the AP-1 family member JunB, whose activity is transcriptionally regulated, is increased in psoriasis and localizes to keratinocyte nuclei within the hyperplastic epidermis of psoriasis lesions." (PMID 24909886, 2014). "AP-1 transcription factor superfamily (including JUN, JUNB, JUND, FOS, FOSB, FRA1, and FRA2) is essential in the pathogenesis of psoriasis." (PMID 35075118, 2022). "To further validate findings from our transcriptional analysis, we performed immunohistochemical analysis focusing on selected apoptotic and cell cycle regulatory proteins (FOSL1, GDF15, JUNB and CDKN1A) in lesional psoriasis skin (control) and 24 h after 311 nm or 290 nm irradiation." (PMID 33812333, 2021).
psoriasis (continued). "Here, we unraveled another member that is N4BP1, plays critical role both in keratinocytes and neutrophils by directly controlling mRNA stability of several key genes including JunB, FosB, and CXCL1, and through such mechanism maintains skin hemostasis to prevent the development of psoriasis." (PMID 33990547, 2021). "However it was also shown that immune-compromised HIV patients exhibit the same rate of psoriasiform dermatitis as the general population and that a complete inactivation of Rag2 in a JunB/JunC mouse psoriasis model did not prevent the development of the disease." (PMID 27050272, 2016).
melanoma (21 papers, 2010 to 2025). A malignant, usually aggressive tumor composed of atypical, neoplastic melanocytes. "Expression of TAM67 caused increased expression of SOX10 in both human melanoma (∼2 folds) and melanocytes (∼3 folds), indicating some relief of JunB inhibition." (PMID 21203491, 2010). "The expression levels of JunB in melanoma-associated microglia were heterogeneous." (PMID 37894348, 2023). "We recognized a diverse range (high and low) of JunB expression levels in melanoma-associated microglia, and therefore sought to establish two different microglia populations, expressing high or low levels of JunB, and to delineate their involvement in melanoma brain metastasis progression." (PMID 37894348, 2023). "Mechanistically, TRIM28 promotes the invasiveness of melanoma cells and inhibits tumor growth by negatively regulating the expression of Jun B proto-oncogene (JUNB)." (PMID 39100077, 2024). "c-Jun, JunB, and C/EBPβ promote glycolysis in melanoma cells through transcriptionally activate genes for glycolysis enzymes and consequentially weaken the anticancer effect of CD8+ T cells." (PMID 38402198, 2024). "Put together, melanoma-derived factors segregate microglia into cell populations expressing high or low (basal level) JunB." (PMID 37894348, 2023). "Altogether, these data highlight a melanoma-mediated heterogenous effect on microglial JunB expression, dictating the nature of their functional involvement in MBM progression." (PMID 37894348, 2023). "Here, we identified the transcription factor JunB to be dramatically upregulated in microglia following their exposure to melanoma." (PMID 37894348, 2023). "Overall, we identified microglia highly expressing JunB as a determinant of the progression of brain-metastasizing melanoma cells." (PMID 37894348, 2023). "To determine if microglia expressing high JunB levels are involved in regulating the migratory capacity of melanoma cells, we performed wound-healing assays of MBM cells in the presence of JunBhi or JunBlo microglia-derived secreted factors." (PMID 37894348, 2023). "Western blot analysis showed that EC359 indeed abrogated JunB upregulation in microglia treated with MCM of three out of four melanoma cell lines, excluding CM of M16.CB3 cells." (PMID 37894348, 2023). "In melanoma, Dac51 enhances m6A modification levels in JunB and C/EBPβ mRNA by inhibiting FTO, which facilitates the binding of YTHDF2 to both mRNAs, leading to significant reductions in JunB and C/EBPβ expression." (PMID 37582735, 2023). "Further analysis of melanoma-exposed microglia recognized the existence of microglia cells with diverse (high or low) expression of JunB." (PMID 37894348, 2023). "The population of microglia expressing low levels of JunB, on the other hand, exhibited an anti-tumor phenotype, attenuating melanoma progression." (PMID 37894348, 2023). "A population of microglia highly expressing JunB exhibited a pro-tumor phenotype, contributing to an immunosuppressive microenvironment, with a modified secretome that promoted melanoma gene expression alterations." (PMID 37894348, 2023). "In the next series of experiments, we asked if JunB-expressing microglia are involved in regulating the malignant phenotype of neighboring melanoma brain metastases." (PMID 37894348, 2023). "TRIM28 depletion therefore leads to higher JUNB expression followed by increased melanoma growth and decreased melanoma invasiveness." (PMID 36341538, 2023). "Among those we found JunB, B2M, and Narf2—markers of inflammation, cell exhaustion, and melanoma oncogenic programs taking place in malignant and T cells." (PMID 34872616, 2021). "Additionally, a recent study reported elevated PD‐L1 levels in microglia subpopulations overexpressing JUNB, which regulate melanoma brain‐metastasis progression." (PMID 39575761, 2025).
melanoma (continued). "Using a combination of data mining, functional perturbations, protein interactome analysis, and in vivo tumor engraftment, we have identified new roles for the bromodomain protein TRIM28, and the transcription factor JUNB, in controlling melanoma growth and metastasis." (PMID 36341538, 2023). "In a mouse model of melanoma, deficiency of JunB in Tregs could release anti-tumor potential of CD4+ T cells, suggesting JunB enhances Treg-mediated immune tolerance in tumorigenesis." (PMID 37731821, 2023). "Indeed, we identified JunB-expressing microglia/TAMs adjacent to melanoma lesions, emphasizing the significance of delineating the role of JunB in MBM-associated microglia/TAMs." (PMID 37894348, 2023). "We measured NO production by melanoma-exposed microglia cells expressing low levels of JunB." (PMID 37894348, 2023). "Genome-wide expression analysis revealed that BRAFV600E-induced melanoma is accompanied with highly enriched c-Jun, JunB, and c-Fos, we thus wonder whether similar AP-1 factors function in PTC development." (PMID 35332119, 2022). "Importantly, among the TGF-beta target genes that were upregulated in our RNA-seq dataset are CD271, SNAI1, and JUNB, which are all known regulators of melanoma phenotype switching." (PMID 32123577, 2020). "Microglia highly expressing JunB may serve as a target for brain-metastasizing melanoma therapy." (PMID 37894348, 2023). "Moreover, we described the mechanism by which JunB upregulation is induced by melanoma cells." (PMID 37894348, 2023). "The fact that microglial JunB may exert the same effects on the malignancy phenotype of different melanoma cell lines through different mechanisms, highlights again, as we have already demonstrated, the issue of intertumor heterogeneity with respect to tumor–microenvironment interactions." (PMID 37894348, 2023). "In melanoma cells, FTO promotes glycolytic metabolism through the activation of c-Jun, JunB, and CCAAT/enhancer binding protein β (C/EBPB)." (PMID 40532011, 2025). "Melanoma-derived factors, namely leukemia inhibitory factor (LIF), controlled JunB upregulation through Janus kinase (JAK)/signal transducer and activator of transcription 3 (STAT3) signaling." (PMID 37894348, 2023). "Our findings provide mechanistic evidence suggesting microglial JunB, as a switch molecule, induced by the neighboring melanoma cells to harness microglia in their favor, and targeting this specific microglia subpopulation may serve as a therapy for brain-metastasizing melanoma." (PMID 37894348, 2023). "Reciprocal signaling between melanoma brain metastatic (MBM) cells and microglia reprograms the phenotype of both interaction partners, including upregulation of the transcription factor JunB in microglia." (PMID 37894348, 2023). "In A375 melanoma cells, knockdown of CD274, MCL1, and JUNB decreased cell survival, and in OAW28 ovarian cystadenocarcinoma cells, knockdown of MCL1 and JUNB decreased cell survival." (PMID 35338135, 2022). "Our screen identifies four candidate genes (CD274 (PD-L1), MCL1, JUNB, and B3GNT2) that, upon upregulation, enable human melanoma cells to evade T cell killing in diverse cancer cell types and mouse xenografts." (PMID 35338135, 2022). "Importantly, CD271, SNAI1, JUNB, and FOSB, the latter two as part of the AP-1 transcription factor complex, are all known regulators of melanoma phenotype switching." (PMID 32123577, 2020).
melanoma (continued). "Notably, both JUNB and JUND are downregulated in invasive/late (stage 4) melanoma compared to stage 1 melanoma, and several DE genes from stage 1 vs. stage 4 comparison enriched in MAP kinase and Ras GTP binding processes." (PMID 32079144, 2020). "Because the MDA-MB-435 cells originated from melanoma, FOXC1 and JunB might be more functionally active in MDA-MB-435 cells than in HeLa cells." (PMID 24815916, 2014). "Over-expression of JunB, but not Jun D, effectively inhibited Sox10 expression in both the melanoma and melanocytes cells." (PMID 21203491, 2010). "The 3D co-cultures of melanoma with JunB-overexpressing microglia protected melanoma cells from the growth-restraining effect mediated by LIFR inhibition, further confirming that LIFR positively regulates MBM cell proliferation predominantly by microglial JunB." (PMID 37894348, 2023). "Therefore, we focused on the LIF/LIFR axis and demonstrated (in three out or four MBM cell lines used in this study) that microglial LIFR activation by LIF in melanoma-exposed microglia induces downstream signaling of the JAK/STAT3 pathway, leading to JunB upregulation." (PMID 37894348, 2023). "Interestingly, TNF-α signalling via the NF-κB pathway was significantly downregulated with a reduction ranging from 7- to 40-fold in expression of some of its prooncogenic target genes (e.g., JUNB, FOS, DUSP1) and melanoma-related genes (e.g., EGR3, NR4A3, CCN1)." (PMID 34497073, 2021). "Correspondingly, JunB, which is required for ATF2-dependent inhibition of Sox10 transcription, is no longer found on the promoter of SOX10 in melanoma cells (i.e. 501Mel) that exhibit positive regulation by ATF2." (PMID 21203491, 2010). "In order to determine whether JunB lost its ability to elicit negative regulation of SOX10 and MITF in melanoma cells where ATF2 no longer inhibited SOX10 or MITF expression, we transfected those cell lines with TAM67 and JunB alone and in combination." (PMID 21203491, 2010).
lung carcinoma (19 papers, 2014 to 2025). "The regulation of Smad target gene expression by m6A methylation is also involved in modulating JUN (encoding c-Jun) and JUNB (encoding JunB) expression during EMT in lung cancer cells." (PMID 38569937, 2024). "MiR-663 decreased the activity of AP-1 by targeting JunB and JunD transcripts, and its upregulation decreased the levels of miR-155, which has been linked to formation and development of tumours such as breast, gastric, and lung cancers." (PMID 25254214, 2014). "A previous study from our group, involving a smaller cohort of lung cancer patients, revealed similar biomarker expression levels, indicating that elevated expression of CXCR4 and JUNB is associated with poorer OS in extended‐stage SCLC." (PMID 39575761, 2025). "METTL3 positively regulates JUNB mRNA stability as well as m6A modification enrichment to affect epithelial‐mesenchymal transition in lung cancer cells." (PMID 38585432, 2024). "Taken together, we concluded that the m6A_1 and m6A_2 sites of JUNB 3′UTR were responsible for m6A-mediated regulation of JUNB mRNA in A549 lung cancer cells." (PMID 36183833, 2022). "Overall, our results demonstrated that both common and individual functions of JUN and JUNB TFs were important in the transcriptional regulation during EMT of lung cancer cells." (PMID 36183833, 2022). "For instance, METTL3 can exacerbate EMT in gastric cancer by activation of the zinc finger MYM-type containing 1 signaling, while it can also upregulate the JunB proto-oncogene to mediate the progression of EMT in lung cancer." (PMID 34666602, 2021). "METTL3 contributes to TGF-β induced epithelial-mesenchymal transition through the regulation of JUNB in lung cancer." (PMID 34277630, 2021). "Another RAC GTPase and catalytic subunit of NADPH oxidase, RAC2, has also been described to promote transcriptional activation of JUNB in lung cancer (Figure 3iii), which could be yet another mechanism that leads to NFIX activation." (PMID 36901722, 2023). "Gene expression analyses in A549 JUNB WT and mut cell clones and in A549 JUNB-ER and control cells, however, failed to confirm that JUNB played a role in the TGFβ1-mediated regulation of these genes in the lung cancer cell line." (PMID 36672507, 2023). "The transcription factor JUNB is essential in cell proliferation and differentiation during development but is also involved in invasion and metastasis, and is implicated in pathways related to EMT, in several neoplasms including lung cancer." (PMID 36612166, 2022). "Consequently, JUNB and CXCR4 were expressed in CTCs from lung cancer patients, and associated with patients’ survival, underlying their key role in tumor progression." (PMID 36612166, 2022). "Likewise, an m6A methyltransferase, methyltransferase‐like 3 (METTL3) has been reported to promote transforming growth factor‐β‐dependent EMT in lung cancer by regulating the transcription factor JUNB." (PMID 33931980, 2021). "Considering the essential role of JunB in Th2 cells-mediated cytokines production during allergic asthma, further exploration is warranted to determine whether it also exerts regulatory functions within the microenvironment of lung cancer." (PMID 37731821, 2023). "The presence of JUNB and/or CXCR4‐positive CTCs correlated with shorter overall survival (OS) and progression‐free survival (PFS) in metastatic breast and lung cancer patients." (PMID 39575761, 2025). "We previously identified JUNB and the chemokine receptor CXCR4 as prognostic biomarkers for breast and lung cancer." (PMID 39575761, 2025). "Our previous research highlighted the clinical relevance of transcription factor JunB (JUNB), C‐X‐C chemokine receptor type 4 (CXCR4), and programmed cell death 1 ligand 1 (PD‐L1) in breast and non‐small cell lung cancer (NSCLC) patients." (PMID 39575761, 2025). "Recently, it was found that both JunB and c-Jun were upregulated in TGF-β1 treated lung cancer cell lines, A549 and LC2/ad." (PMID 37731821, 2023).